PLAU (plasminogen activator, urokinase)
Diseases named in the same sentence as PLAU in open-access papers (continued):
Sharing a sentence is not in itself a finding about the gene and the disease.
cancer (continued). "In the older TNBC cohort, myeloid cells and CAFs interact with cancer basal cells through LGALS9/P4HB, PPIA/BSG, and PLAU/PLAUR ligand/receptor pairs to promote EMT and cell motility, as confirmed by the age-related increase in EMT ARPs." (PMID 39483921, 2024). "The results exhibited that the mRNA and protein expression levels of PLAU, APP, AREG and CAV2 were upregulated in cancer cells compared to normal cells." (PMID 36437265, 2022). "KEGG pathway analysis suggests that PLAU and PLAUR are mainly involved in the proteoglycan-related cancer signaling pathway, Wnt signaling pathway, and TNF signaling pathway." (PMID 35087738, 2021). "Three proteins (PLAU, ZEB1, and MITF) were involved in the “transcriptional misregulation in cancer”." (PMID 34408977, 2021). "Four proteins (PLAU, ITGA5, ZEB1, and ERBB3) were involved in “microRNAs in cancer” signaling pathway." (PMID 34408977, 2021). "These cytokines have been identified to be directly or indirectly responsible for cancer progression through remodeling of ECM by upregulating the expression of molecules such as MMP2, MMP3, MMP9, MMP10, MMP13, PLAU, ICAM1 and VCAM1." (PMID 34946170, 2021). "Expression of genes that played a pivotal role in cancer cell migration, including VEGFA, PLAU, MMP2, MMP9, and MMP14, were reduced in dose-dependent manner of stigmasterol in both cell lines." (PMID 32481565, 2020). "For improving the understanding of SEMA6A-derived migration pathway, we also determined the mRNA expression levels of PLAU, MMP1 and MMP9 using RT-qPCR, because these genes were indicated to be reduced by HMOX1 and to induce migration in cancer cells." (PMID 31527696, 2019). "This enabled us to examine genes on an individual basis, and many genes important in the development of CRC, and cancer in general, were upregulated in the CAP tissues relative to the CFPs, including CXCL5, GREM1, IGF2, CTGF and PLAU." (PMID 29453410, 2018). "The 2Chr7:1n,1d cells exhibited a more invasive phenotype by expressing higher levels of the pro-invasive genes (IGFBP2, PDGFRA, RHOC, FOXM1, and PLAU) and matrix metalloproteinase 2 (MMP2), all of which are well-reported for cancers, including GBM." (PMID 24282558, 2013). "From a clinical point of view, IL1RN, MAL and TGM3 were not clearly identified as potential HNSCC markers, while few data have been published concerning the implication of FN1, KRT, MMP1, PLAU and SPARC in this type of cancer." (PMID 19835631, 2009). "Gene set enrichment analysis (GSEA) also revealed a significant downregulation of the hypoxia pathway and HIF-1α target genes upon ASH1L depletion, particularly those involved in cancer cell invasion (Snail, TGFB, and MET), extracellular matrix remodeling (MMPs and PLAU), and angiogenesis (VEGFs)." (PMID 40394007, 2025). "In scRNA-seq, however, PLAU was predominantly expressed in CAFs and pericytes, but not in cancer cells." (PMID 40075643, 2025). "The PLAU-PLAUR interaction regulates the proliferation, migration, and invasion of cancer cells." (PMID 38229120, 2024). "For example, APOE, PLAU, CDK1 and MUC1 were significantly higher in TNBC tissues than in cancer-parasite tissues, whereas PDGFRB, RET, ROCK2, CCND1 and PPARA were significantly lower in TNBC tissues than in cancer-parasite tissues." (PMID 38329441, 2024). "Notably, increased expression of these hub genes correlated with advanced cancer stages and decreased patient survival, particularly LAMC2 and PLAU, suggesting their potential as prognostic biomarkers." (PMID 38707175, 2024). "We could detect upregulated genes as well (PLAU, SERPINA1, and AKT3), mainly connected to cancer development and progression and mesenchymal phenotypes, that were also responsive to EZH2 inhibition." (PMID 38672463, 2024). "It suggests that PLAU and TOP2A may be dangerous biomarkers and potential therapeutic targets for PCa and other cancers." (PMID 36741321, 2023). "PLAU is one of the potential biomarkers for HNSCC and several other cancers." (PMID 36203433, 2022).
cancer (continued). "Several groups have attempted to measure uPA (also known as the PLAU gene) and PAI-1 (also known as SERPINE1) mRNAs in cancer through quantitative reverse transcription-polymerase chain reaction (qRT-PCR) and nucleic acid sequence-based amplification (NASBA) assays." (PMID 33921923, 2021). "Interestingly, only PLAU and KIF5C were elevated in cancer tissues compared to adjacent normal tissues." (PMID 31844033, 2019). "Because WA predominantly increased DNA methylation, we mainly focused on verification of hypermethylation effects obtained for selected genes related to cancer invasiveness (ADAM8, PLAU, and TNFSF12), detoxification (GSTM1) or mitochondrial functions (ME3), in relation to gene expression silencing." (PMID 28467815, 2017). "Importantly, we observed that several other cancer-promoting genes including CTGF, PLAU and PLA2G7 were induced in macrophages during macrophage-NPC interaction." (PMID 27487154, 2016). "Cancer cells of growing ribociclib-resistant tumors used a diverse set of M2-like differentiation stimulating communication pathways as shown by a range of markers: CSF1, CLCF1, several FGFs (1/2/7/17/18/23), the TGF family member GDF9, interleukin 5/11/12, MADCAM1 and PLAU." (PMID 40032842, 2025). "Interestingly, degradation of BM including type IV COL is rate-limiting step for cancer intravasation into blood in metastasis, and PLAT as well as PLAU may be the initial members of the protease cascade." (PMID 38557819, 2024). "PLAU, as a top identified molecule, inhibits various biological functions such as NADH due to its role in energy production and may help against wastage and weakness of cancer patients." (PMID 36203433, 2022). "Specifically, ANLN, ARNTL2, TOP2A, PLAU, and VCAN expression are important in the invasion of the basement membrane, intravasation, extravasation, and colonization at secondary sites, but only TOP2A and ARNTL2 contribute to the survival of cancer cells while in circulation." (PMID 34591244, 2021). "In addition, catalytically inactive PLAU also promotes cell migration via binding to PLAUR and initiation of intracellular signaling mediated by integrins; along with other PLAUR co-receptors in cancer cells, neutrophils, endothelial and smooth muscle cells." (PMID 29254187, 2017). "Berberine also showed anti-metastatic properties in several cancer cell lines, acting on 72 kDa type IV collagenase (MMP2), Cdc42 effector protein 1 (CDC42EP1), and ras-related C3 botulinum toxin substrate 1 (RAC1), transforming protein RhoA (RHOA) and urokinase-plasminogen activator A (PLAU)." (PMID 23213296, 2012). "Recent reports shed light on PLAU/PLAUR roles that are not directly related to cell migration; thus, PLAUR affects epithelial-to-mesenchymal transition, stemness properties of cancer cells, metabolic state of cancer cells." (PMID 29254187, 2017).
infection (12 papers, 2009 to 2024). The state of being infected such as from the introduction of a foreign agent such as serum, vaccine, antigenic substance or organism. "Based on our results, we propose that coordinated expression of VEGFA and PLAU plays an important role in the inflammatory response of macrophages to CSFV Shimen infection." (PMID 30849965, 2019). "In conclusion, we showed that VEGFA and PLAU were significantly up-regulated after CSFV Shimen infection." (PMID 30849965, 2019). "Quantitative polymerase chain reaction and western blot analysis confirmed that VEGFA and PLAU were significantly up-regulated at both the transcription and translation levels after infection." (PMID 30849965, 2019). "Our findings suggest that co-expression of VEGFA and PLAU in macrophages contributes to CSFV Shimen infection and serves as a significant avenue for the strain to form an inflammatory microenvironment, providing new insight into the mechanisms of CSF caused by a virulent strain." (PMID 30849965, 2019). "Matching the data collected during the physical characterization of the NTHi-NHNE infection, expression levels of key chemo- and cytokines (e.g. CXCL8, IL-6, IL-1β, CCL3, CXCL1 & CXCL2) and genes involved in ECM remodelling and inflammation (PLAU, Serpine1, MMP9) increased further on day14." (PMID 38990812, 2024). "Venn diagram analysis showed that among the common DGEs in the 3 h and 12 h infection groups compared with the control group, 11 differential genes were enriched in the NF-κB signaling pathway, including CXCL8, IL-1β, CCL4, IκBα, TNF, NF-κB, CFLAR, PTGS2, TRAF1, PLAU, and IL-1β2." (PMID 35215890, 2022). "Some of these genes belong to the NF-kappa B (NF-κB) (PLAU, VCAM1, TNFRSF1A) and/or mitogen-activated protein kinase (MAPK) (TNFRSF1A and PGF) signaling pathways, indicating a differential regulation of the inflammatory response in lungs for both infection outcomes." (PMID 35003125, 2021). "In the absence of infection, CF-TG cells constitutively exhibited an inflammatory signature, including genes that encode molecules such as IL-1α, IL-β, IL-32, TNFSF14, LIF, CXCL1 and PLAU." (PMID 19399182, 2009).
bacterial infection (3 papers, 2015 to 2021). "The PLAU-deficient mice failed to develop T cells and macrophages and thus dying of bacterial infection was once reported." (PMID 35087738, 2021). "The relative MoDC vs. Mo/MP signature encompasses additional genes that participate in “migration of cells” (p = 10−2.3, with S1PR3, CCL17, and SLC2A1), “bacterial infection” (p = 10−3.2, with CD1B, CD209, and FCGR2B), and “synthesis of nitric oxide” (10−2.5, with PLAU, IL1R2, and NOS2)." (PMID 26150816, 2015).
neurodegenerative disease (2 papers, 2019 to 2025). A disorder of the central nervous system characterized by gradual and progressive loss of neural tissue and neurologic function. "Our data suggest that the well-known effect of dietary n3-PUFA intake on the development of neurodegenerative diseases may be connected to improved beta amyloid degradation through the upregulation of expression of plasminogen activator (PLAU)." (PMID 31756991, 2019).
neurological disorder (2 papers, 2019 to 2022). "The PLAU p.Cys151Phe was inherited from the father (I-1), who at 71 years of age did not report suffering from MS symptoms or any neurological disorder." (PMID 31170158, 2019).
vasculopathy (2 papers, 2021 to 2025). "The downregulation of PLAU aligns with impaired fibrinolysis observed in GD1-associated bone crises, while COL4A1 overexpression may reflect aberrant angiogenesis, a feature increasingly recognized in GD1 vasculopathy." (PMID 41323100, 2025). "Although it was not confirmed if the PLAU c.664G>A identified in our subject was a loss-of-function variant, the results of our zebrafish experiments and those of the previous mouse study suggest the possibility of PLAU-associated vasculopathy in humans." (PMID 34354133, 2021).
kidney-disease (1 paper, 2021). "Associated variants were found in and around genes encoding uPAR (PLAUR), its ligand uPA (PLAU), the kidney-disease-associated gene PLA2R1 as well as genes with relations to glycosylation, glycoprotein biosynthesis, and the immune response." (PMID 34079037, 2021).
skeletal anomaly (1 paper, 2021). "In conclusion, two de novo variants were discovered in the EP300 and PLAU genes of a patient with RSTS-related skeletal anomaly and characteristic peripheral arterial vasculopathy." (PMID 34354133, 2021).
PLAU also shares sentences with these, for which no sentence is quoted: severe combined immunodeficiency (5 papers); breast (4); Sepsis (4); virus infection (4); aortic aneurysm (3); neuroblastoma (3); prostate (3); renal cell carcinoma (3); acne (2); acute myeloid leukemia (2); acute myocardial infarction (2); adenoma (2); aortic stenosis (2); artery occlusion (2); Arthritis (2); astrocytoma (2); cardiovascular disease (2); colitis (2); coronary artery disease (2); deep vein thrombosis (2); endometrial cancer (2); Ewing sarcoma (2); focal segmental glomerulosclerosis (2); gastric adenocarcinoma (2); heart failure (2); Hodgkins lymphoma (2); Hypertension (2); Immunodeficiency (2); multiple myeloma (2); multiple sclerosis (2).
A further 67 diseases each share a sentence with PLAU in 2 papers or fewer.